STK36 (serine/threonine kinase 36)
Description:
Serine/threonine protein kinase which plays an important role in the smoothened pathway by regulating the activity of GLI transcription factors. Controls the activity of the transcriptional regulators GLI1, GLI2 and GLI3 by opposing the effect of SUFU and promoting their nuclear localization. Acts by mediating phosphorylation of GLI proteins, promoting their dissociation from SUFU. Also catalyzes phosphorylation of ULK4 adapter. GLI2 requires an additional function of STK36 to become transcriptionally active, but the enzyme does not need to possess an active kinase catalytic site for this to occur. Required for postnatal development, possibly by regulating the homeostasis of cerebral spinal fluid or ciliary function. Essential for construction of the central pair apparatus of motile cilia.
Synonyms: KIAA1278; FU; CILD46
Tractability: Small molecule: a high-quality ligand is known; it belongs to a druggable protein family. Antibody: its Gene Ontology location is reachable by antibodies, with medium confidence. PROTAC: ubiquitination databases record sites on it; a small molecule that binds it is known.
Target class: Kinase; Other protein kinase group; Other protein kinase ULK family; Enzyme; Protein Kinase
Gene: Protein-coding gene on chromosome 2 (218,672,052 to 218,702,717, forward strand). Ensembl gene ENSG00000163482.
Subcellular location: Cell projection, cilium; Cytoplasm, cytoskeleton, cilium axoneme; Cytoplasm; Nucleus
Subcellular location (Human Protein Atlas): Cytosol
Gene Ontology:
Molecular function: protein binding; protein serine/threonine kinase activity; transcription corepressor binding; ATP binding; protein serine kinase activity; protein kinase activity
Biological process: axoneme assembly; cilium assembly; positive regulation of smoothened signaling pathway; smoothened signaling pathway; post-embryonic development; microtubule-based process
Cellular component: ciliary tip; cytoplasm; cytosol; nucleus; axoneme; cilium
Genetic constraint (gnomAD): Loss-of-function variants: 116 observed, 148.33 expected, observed/expected ratio (o/e) 0.78, 90% interval 0.67 to 0.91. The upper end of that interval is the gene's LOEUF score, 0.91, which puts it in group 3 of 6, group 1 being the genes least tolerant of losing a copy. Missense variants: 1,422 observed, 1,695.8 expected, observed/expected ratio (o/e) 0.84, 90% interval 0.8 to 0.88. Synonymous variants: 619 observed, 675.26 expected, observed/expected ratio (o/e) 0.92, 90% interval 0.86 to 0.98.
Gene-disease validity (ClinGen):
ClinGen rates the evidence that STK36 causes each of these diseases.
ciliary dyskinesia, primary, 46 (autosomal recessive): Moderate.
Homologues: Orthologues: chimpanzee STK36 (99% identical), macaque STK36 (94% identical), pig STK36 (89% identical), dog STK36 (88% identical), rat Stk36 (85% identical), mouse Stk36 (85% identical), rabbit STK36 (84% identical), guinea pig STK36 (83% identical), tropical clawed frog stk36 (41% identical), zebrafish stk36 (31% identical), Drosophila melanogaster fu (20% identical). Paralogues in human: ULK4 (19% identical).
Diseases named in the same sentence as STK36 in open-access papers:
STK36 is named in the same sentence as 16 diseases in open-access papers, as found by Europe PMC text mining. Sharing a sentence is not in itself a finding about the gene and the disease. The quoted sentences say what the papers report.
breast carcinoma (2 papers, 2014 to 2017). "CBX2 plays a role in epigenetic regulation and hematopoietic stem cell differentiation, whereas the STK32B gene is one of several serine/threonine kinases (STK32B, STK36, and STK39) with similar gene expression patterns in basal-like breast cancers." (PMID 24885002, 2014).
basal cell carcinoma (1 paper, 2017). A carcinoma involving the basal cells. "Pathways that followed were ligand-receptor interactions (IHH, PTCH1) (p-value = 5.76 × 10−5) and signalling in basal cell carcinoma (BMP2, STK36, PTCH1) (p-value = 6.73 × 10−5)." (PMID 28117334, 2017).
epileptic encephalopathies (1 paper, 2016). "Recently, de novo mutations in STK36 have been identified in patients with epileptic encephalopathies." (PMID 27282200, 2016).
glioblastoma multiforme (1 paper, 2024). "Previous studies found that STK36 can intervene in the response of glioblastoma multiforme to temozolomide and a pathological variant of gastric cancer." (PMID 38184689, 2024).
liver fibrosis (1 paper, 2016). "In the current study, the Hh-related genes, including Bmp4, Gas1, Gli3, Hhip, Ihh, Prkacb, Stk36, Wnt6, Wnt10b, Wnt9a and Wnt11, were dysregulated in our murine model of CCl4-induced liver fibrosis." (PMID 27322257, 2016). "Although four other Hh-related genes, including Gas1, Prkacb, Stk36 and Wnt9a, were significantly downregulated with the simultaneous upregulation of their regulator miRNAs in the CCl4 group compared to the control group, the roles of these Hh-related genes in liver fibrosis is poorly understood." (PMID 27322257, 2016).
male infertility (1 paper, 2024). The inability of the male to effect fertilization of an ovum after a specified period of unprotected intercourse. "Therefore, we hypothesize that the significant downregulation of DEGs (CFAP70, TTC29, CCDC40, DNAAF4, SYCE3, STK36, SPI1 and EMX2) in hybrid yellow catfish is the primary cause of male infertility or reduced fertility." (PMID 38891632, 2024).
medulloblastoma (1 paper, 2022). A malignant, invasive embryonal neoplasm arising from the cerebellum. "Indeed, combined depletion of Ulk3 and Stk36 resulted in more dramatic reduction of Hh pathway activity as well as Smo-driven medulloblastoma growth than depletion of either Ulk3 or Stk36 alone." (PMID 35186941, 2022).
Pancreatic cancer (1 paper, 2013). "On the other hand up regulation of SHH, STK36, ERK12, RAS and down regulation of SUFU were co-occurring in Pancreatic cancer cell line, hence in our second simulation (Simulation 2), we considered all these co-occurrence as initial states to provide biologically realistic predictions." (PMID 23935937, 2013).
promyelocytic leukemia (1 paper, 2025). "To determine whether SUMOylation and SIM mediates Ulk4 condensation as is the case for promyelocytic leukemia (PLM) bodies, we co-expressed Stk36-EE with wild-type (Ulk4-WT), SUMOylation deficient (Ulk4-K1030R) or SIM-mutated Ulk4 (Ulk4-ΔSIM) in HEK293T cells." (PMID 40171800, 2025).
prostate carcinoma (1 paper, 2024). A carcinoma that arises from epithelial cells of the prostate gland. "This study found that STK36 has an impact on various biological phenotypes of prostate cancer cells." (PMID 38184689, 2024). "Whether STK36 is a good candidate target in clinical trials and can be used as an adjuvant for the treatment of docetaxel resistant prostate cancer with docetaxel requires further in vivo confirmation, which is also our next research direction." (PMID 38184689, 2024). "Involuntary, these deserve a suspicion that STK36 probably conserves a potential correlation with docetaxel, especially under the state that its function is still not clear in prostate cancer." (PMID 38184689, 2024).
cancer (3 papers, 2013 to 2024). A tumor composed of atypical neoplastic, often pleomorphic cells that invade other tissues. "By analyzing the GSE4660227, GSE2103228, and the cancer genome atlas (TCGA) datasets, STK36 mRNA levels were significantly increased in PCa tumor tissue samples from patients." (PMID 38184689, 2024). "We observed that although the activation pathways (broken red arrows)from SMO to GLI1 and GLI2 via STK36 protein were blocked by the effect of SMO inhibitor in each cancer scenario, HFU could also activate GLI1 and GLI2 in each cancer scenario (solid green arrows)." (PMID 23935937, 2013).
tumor (3 papers, 2012 to 2024). "In summary, our data suggested that overexpression of STK36 has a force-tumor effect in models of docetaxel-sensitive PCa." (PMID 38184689, 2024). "The expression of STK36 was positively correlated with pathological pattern (P < 0.0001), Gleason score (Homogeneity of variance test P-value 0.717, one-way ANOVA P = 0.027), and tumor Grade (P = 0.044)." (PMID 38184689, 2024).
STK36 also shares sentences with these, for which no sentence is quoted: infection (2 papers); epilepsy (1); glioma (1); neurodegenerative disease (1).